ICAM1 (intercellular adhesion molecule 1)
Diseases named in the same sentence as ICAM1 in open-access papers (continued):
Sharing a sentence is not in itself a finding about the gene and the disease.
COVID-19 (143 papers, 2020 to 2026). A disease caused by infection with severe acute respiratory syndrome coronavirus 2. "We found an inverse association between genetically predicted macrophage colony stimulating factor (MCSF), soluble intercellular adhesion molecule-1 (sICAM), and soluble vascular cell adhesion molecule-1 with risk of COVID-19 outcomes." (PMID 39319267, 2024). "The ICAM1 gene was found to be upregulated in endothelial cells in lung endothelial cells of COVID-19 victims and was associated with immune hyperactivation in the lungs and circulation." (PMID 39444690, 2024). "Overall, the ICAM1-associated pathways constructed from the data and knowledge in this study will expedite the repair and completion of the COVID-19 Disease Map for a deeper understanding of SARS-CoV-2 pathogenesis." (PMID 37719701, 2023). "Another substantial consequence of revealing ICAM1-associated pathways contributes to completing the COVID-19 Disease Map." (PMID 37719701, 2023). "The increased expression of ICAM-1 in the COVID-19 group suggests that the virus causes significant endothelial damage, leading to systemic inflammation and the potential for further vascular remodeling." (PMID 36992415, 2023). "ICAM-1 is also elevated in endothelial cells of COVID-19 postmortem lung biopsies and associated with endothelial dysfunction and pyroptosis." (PMID 36017003, 2022). "This supports the deleterious role of unbound LA in causing endothelial injury (i.e., elevated E-selectin, ICAM-1) in severe COVID-19 patients and in our mice." (PMID 35502320, 2022). "Our results suggested that ICAM1 showed putative causal effects on COVID-19 severity in both ancestries, with splicing events potentially mediating the effect." (PMID 35772218, 2022). "Resistin was significantly associated with IL-6, IL-8, IL-10, VCAM-1 and ICAM-1 in the COVID-19 patients." (PMID 35784283, 2022). "Contrary to our findings, higher ICAM-1 levels have been associated with COVID-19 severity, requiring follow-up investigations." (PMID 35239653, 2022). "Higher levels of LCTL, SFTPD, KEL, and ATP2A3 were solely associated with a decreased risk of hospitalization (ORs = 0.86–0.93), whilst higher levels of ICAM-1 were solely associated with a decreased risk of respiratory support/death of COVID-19 (OR = 0.84)." (PMID 35239653, 2022). "Consequently, it is significant to uncover the ICAM1-associated pathways to better understand the interactions between cells in the context of COVID-19." (PMID 37719701, 2023). "The comparison between the obtained ICAM1-associated pathways in case study 1 with the COVID-19 Disease Map reveals existing and unknown nodes." (PMID 37719701, 2023). "Another suggested mechanism of disease for COVID-19 is the loss of the endothelial integrity associated with changes in the surface expression of intracellular adhesion molecule-1 (ICAM1), vascular cell adhesion protein-1 (VCAM1) and the tight junction scaffold protein zonula occludens-1 (ZO-1)." (PMID 35050236, 2022). "This is an important finding as it may help develop a strategy for treating COVID-19 since inflammation and blood clotting are linked to regulatory molecules IL-6 and ICAM-1 induced by VPA." (PMID 34674775, 2021). "Therefore, discovering unknown ICAM1-associated pathways will be indispensable for clarifying the mechanism of COVID-19." (PMID 37719701, 2023). "Intercellular Adhesion Molecule 1 (ICAM1) increased notably in severe COVID-19 patients who survived, with an even greater rise in those who died, highlighting its role in leukocyte adhesion and migration during severe inflammation." (PMID 39928675, 2025). "ICAM1 serves as a prognostic marker for long-term complications or sequelae due to COVID-19 infection and an effective biomarker for predicting COVID-19 severity." (PMID 41155463, 2025).
COVID-19 (continued). "Vascular cell adhesion molecule-1 (VCAM-1) and ICAM-1 levels were found to be elevated in the blood of patients with mild COVID-19 and dramatically elevated in severe cases, decreasing during the convalescence phase." (PMID 41583455, 2025). "Increased ICAM-1 levels have been observed in both plasma and post-mortem lung tissues of COVID-19 patients." (PMID 40543387, 2025). "In patients with cirrhosis, elevated plasma ICAM1 acts as an independent predictor of severe COVID-19." (PMID 41155463, 2025). "During hospitalization, s-ICAM-1 concentrations only showed a significant reduction in severe COVID-19 patients at days 3–4 (P < 0.001 vs. Admission), remaining unchanged in both groups of critically ill patients." (PMID 39862311, 2025). "This hyperinflammatory state was accompanied by coagulative disturbances, including elevated D-Dimer, E-sel, ICAM-1, and VCAM-1, aligning with previous studies highlighting COVID-19-associated coagulopathy as a key factor contributing to LC sequelae." (PMID 41226453, 2025). "In this study, we have investigated the impact of IL-17F activation on endothelial cells and its impact on neutrophil recruitment and ICAM-1 expression at the surface level in the context of acute COVID-19." (PMID 39493750, 2024). "Markers that indicate blood vessel damage and endothelial activation, such as Ang-2, ICAM-1, and IL-1β, are elevated in severe COVID-19." (PMID 40008234, 2024). "Despite some variability in the response, we observed an increase in the percentage of ICAM-1 expressing cells following treatment with severe COVID-19 or ARDS sera." (PMID 38041432, 2024). "Increased expression of ICAM-1 was found in post-mortem biopsies of the myocardium of COVID-19 patients, as well as increased indicators of myocardial fibrosis compared to controls." (PMID 39444690, 2024). "The findings from this investigation unveiled heightened plasma levels of key proinflammatory cytokines, including interleukin IL-1β, IL-6, TNF-α, monocyte chemoattractant protein-1, and soluble intercellular adhesion molecule-1 in COVID-19 patients." (PMID 38448675, 2024). "The elevation of specifically ICAM-1 seen in COVID-19 indicates that SARS-CoV-2 is capable of significant endothelial damage." (PMID 40008234, 2024). "In parallel to platelet activation, we evaluated endothelial cell activation and assessed the expression of ICAM-1/CD54 on co-culture with platelets and exposure to COVID-19 plasma." (PMID 37215546, 2023). "Theoretically, ICAM-1 as a mediator of endothelial inflammation was increased in patients with confirmed COVID-19, because SARS-CoV-2 will trigger an inflammatory cascade in cells through its endothelial receptors, which were then known as cytokine storms." (PMID 38465016, 2023). "Results from the array pointed to elevated serum concentrations of integrins such as ICAM1 or hemostasis-related proteins such as SerpinE1 in the serum of COVID-19 patients." (PMID 36759861, 2023). "Reelin level was correlated with IL-1α, IL-4, IP-10, MIP-1β, and ICAM-1, suggesting a specific role for Reelin in COVID-19 progression." (PMID 37441066, 2023). "Whereas the Common Cold cocktail induced albuminuria selectively in the Zhx2 hypomorph state, simply substituting ACE2 for ICAM-1 in Common Cold cocktails (COVID-19 Cocktail A) induced albuminuria in Zhx2+/+ mice." (PMID 37040185, 2023). "We presented increased and sustainable ICAM-1 plasma levels in COVID-19 and post-COVID-19 patients, which were greater in females." (PMID 37896963, 2023). "SOD2 is known as a gene whose expression variation has been confirmed accompanied with ICAM1 in COVID-19." (PMID 37719701, 2023). "Another study also shows that the ICAM-1 level increases in the severe phase and decreases in the convalescent phase of COVID-19." (PMID 37719701, 2023). "the mean value of ICAM-1 levels for patients with confirmed positive COVID-19 cases was higher than those with suspected COVID-19 cases." (PMID 38465016, 2023).
COVID-19 (continued). "Patients with severe COVID-19 are known to have increased vascular inflammation characterized by increased expression of lung endothelial ICAM-1 and VCAM-1, which facilitate the infiltration of inflammatory cells into the lung tissue." (PMID 38143504, 2023). "First reports have shown that serum VCAM-1 and ICAM-1 levels were increased in COVID-19 patients (n = 36), as compared to healthy subjects (n = 16), positively correlating with disease severity and tending to decrease during convalescence." (PMID 36941580, 2023). "The high expression of intercellular adhesion molecule-1 (ICAM-1) by endothelial cells in COVID-19 patients was reported." (PMID 36674700, 2023). "Patients who were positive for COVID-19 based on the results of the RT-PCR test in this study had an average serum ICAM-1 level of about 88 ng/mL (95% CI 36-140 ng/mL, p = 0.001) higher than those who were negative, or not tested." (PMID 38465016, 2023). "In contrast, a study of lung tissue from patients who died from COVID-19 (n = 9) showed a reduced local expression of ICAM-1, VCAM-1, E-selectin, and P-selectin." (PMID 36941580, 2023). "ICAM-1 showed an increased tissue expression (p < 0.0001) in the COVID-19 compared to the CONTROL and H1N1 groups." (PMID 36992415, 2023). "The level of the cell adhesion molecule ICAM-1 was increased in the female COVID-19 patients at diagnosis and was further generally increased in all COVID-19 patients at follow-up, though the increase was greater in females (p < 0.001)." (PMID 37896963, 2023). "Studies have shown the benefits of corticosteroids, such as dexamethasone, in reducing mortality in COVID-19 patients and reducing biomarkers such as ICAM-1 and ANGPT-2." (PMID 36992415, 2023). "Another study shows the opposite result on the decrease of ICAM-1 after immune cell infiltration in COVID-19 while leaving room for controversy regarding the reasons for downregulation." (PMID 37719701, 2023). "Reelin level was highly correlated with IL-1α, IL-4, IP-10, MIP-1β, and ICAM-1, suggesting a specific role for Reelin in COVID-19 progression." (PMID 37441066, 2023). "From these previous arguments, it is assumed that ICAM-1 can be related to SARS-CoV-2 cell-to-cell transmission in COVID-19 patients." (PMID 37719701, 2023). "This research also showed that, out of thirteen targets, the top six (IL-6, PPARG, MAPK3, PTGS2, ICAM1, and MAPK1) are likely to be implicated in the anti-COVID-19 effects of Kochiae Fructus’ active phytomolecules." (PMID 35992697, 2022). "Similar to COVID-19 patients, LA treated mice had higher soluble ICAM-1, and DAMPs (i.e., ds-DNA, HMGB-1, and histone-DNA complex levels) which as we shall discuss later can be pro-thrombotic and pro-inflammatory." (PMID 35502320, 2022). "One protein, ICAM1 showed suggestive effect on COVID-19 severity in both ancestries (OR in Europeans=1.152, 95%CI=1.063 to 1.249, P = 5.94 × 10−4; OR in Africans=1.481, 95%CI=1.008 to 2.176; P = 0.045)." (PMID 35772218, 2022). "In the present study, we showed that ICAM-1 and VCAM-1 were elevated more in COVID-19 patients than in controls and were associated with resistin levels." (PMID 35784283, 2022). "The OAS1, SERPINA1 and ICAM1 effects were replicated using updated COVID-19 severity data in the two ancestries respectively, where alternative splicing events in OAS1 and ICAM1 also showed marginal effects on COVID-19 severity in Europeans." (PMID 35772218, 2022). "The MR analyses using these sQTLs as instruments suggested that alternative splicing events of the OAS1 and ICAM1 in some tissues (including adipose, adrenal gland and artery tissues) showed marginal effects on COVID-19 severity (MR P value<1 × 10−3)." (PMID 35772218, 2022). "Endothelial cell adhesion molecules such as ICAM-1 and VCAM-1, which were also used as endothelial damage markers, were elevated in COVID-19 and associated with disease severity in previous reports." (PMID 35784283, 2022).
COVID-19 (continued). "In the current study, COVID-19 patients had higher levels of ICAM-1 and VCAM-1 than healthy control and the severe group had higher levels than the mild or moderate group, which was consistent with earlier findings." (PMID 35958594, 2022). "The protein expression of E-selectin, VCAM-1 and ICAM-1 was also unaltered in samples incubated with COVID-19 patient plasma compared to mock." (PMID 35837388, 2022). "The plasma levels of VCAM-1, ICAM-1 and IL-8 were also higher in the COVID-19 patients than in the healthy control at every measurement point." (PMID 35784283, 2022). "Ang-2 and ICAM-1 were higher in COVID-19-related ARDS, further highlighting the role of pulmonary vascular injury in this context." (PMID 33608030, 2021). "A statistically significant increase in sVEGFR1 levels above HVs was apparent in the most severely ill patients with COVID-19, while modest changes were observed for soluble ICAM-1 (sICAM-1) and soluble E selectin (sE selectin; also known as sCD62E)." (PMID 33232303, 2021). "The results of clinical research suggested that in severe COVID-19 patients, intercellular adhesion molecule 1 (ICAM-1), also known as cluster of differentiation 54 (CD54), was significantly elevated, but it was reduced during the recovery period." (PMID 34177566, 2021). "ICAM-1, which controls the firm adhesion of neutrophils on the endothelium, has been extensively studied in relation to non-COVID-19 ICU outcome; ICAM-1 production has been shown to be associated with increased mortality." (PMID 33477776, 2021). "In our study, it was observed that ICAM1 levels were higher in COVID-19 cases on the 7th and 14th days of the treatment compared with controls." (PMID 34836309, 2021). "Here, we demonstrate that the expression of KLF2 was reduced and monocyte adhesion was increased in endothelial cells treated with COVID-19 patient serum due to elevated levels of pro-adhesive molecules, ICAM1 and VCAM1." (PMID 34253708, 2021). "In detail, Ang-2, ICAM-1 and E-selectin were higher in COVID-19-related ARDS (all p < 0.001 for group comparison), whereas RAGE and P-selectin levels were higher in classical ARDS." (PMID 33608030, 2021). "Serum levels of ICAM-1 reduced significantly in patients with DFU in the COVID-19-positive group were significantly higher than those in the COVID-19-negative group after debridement (median 312.5 vs 130.3; p < 0.001)." (PMID 33585030, 2021). "It was observed that ICAM1 levels were higher in COVID-19 cases on the 7th and 14th day of the treatment compared with controls." (PMID 34836309, 2021). "There were notable differences in ICAM-1 levels between the COVID-19 and non-COVID-19 groups at baseline and even after debridement (p < 0.001)." (PMID 33585030, 2021). "Proteomic profiling of blood samples from COVID-19 patients identifies ICAM-1 and FCGR3A (CD16) as the most significant proteins in the classification of short vs. extended disease course (Tang)." (PMID 32848776, 2020). "Similarly, several studies have shown increased levels of ICAM1 in serum of patients recovered from COVID-19." (PMID 39739157, 2024). "Furthermore, this was mirrored by a significant increase in ICAM-1 mean fluorescence intensity (MFI) in the severe COVID-19 and ARDS cell cohorts compared to the controls." (PMID 38041432, 2024). "Thus, we monitored ICAM-1 in the vascular walls of human lung sections from patients who died of COVID-19." (PMID 38771750, 2024). "Elevated ICAM1 in plasma, which could be released by the damaged endothelium, is also positively correlated with disease severity, as has been observed in COVID-19 patients." (PMID 39739157, 2024). "One study shows the time-dependent ICAM-1 expression level changes in COVID-19 patients." (PMID 37719701, 2023).
COVID-19 (continued). "Tight junction integrity disruption leads to increased transmigration of neutrophils, platelet and leukocyte adhesion, and transendothelial migration and cardiovascular diseases and increased ICAM-1 expression facilitates virus entry and severe COVID-19 development." (PMID 36674700, 2023). "Dexamethasone reduces angiopoietin-2 (Ang-2), intercellular adhesion molecule 1 (ICAM-1), glycocalyx shedding and the soluble receptor for advanced glycation end-products (sRAGE) in critically ill COVID-19 patients, suggesting potential reduction in endothelial damage." (PMID 37515150, 2023). "A few genes, as NFKBIA, ICAM1, CXCL8, and TNFAIP3 are involved in NF-κB signaling and TNF signaling pathways, which have been known to cause inflammation and cytokine storms, augmenting COVID-19 severity." (PMID 37701571, 2023). "Indeed, the time-dependent change of the ICAM-1 expression level has been detected in COVID-19 patients." (PMID 37719701, 2023). "In addition to TNF-α, the levels of the adhesion molecules ICAM-1 and E-selectin were greatly increased, especially in female COVID-19 patients." (PMID 37896963, 2023). "As a summary of contributions, this study discovered novel ICAM1-associated pathways currently absent from the COVID-19 Disease Map." (PMID 37719701, 2023). "Interestingly, the results were consistent with those in COVID-19; 27 of the IRGs were highly expressed in myeloid cells, except Icam1, Lyn, Cybb, Casp1, Gbp1, Vnn2, Socs3, Bcl2a1 and Lcn2 genes." (PMID 36817436, 2023). "Removing ICAM-1 in the Common Cold cocktail and adding sACE2 resulted in COVID-19 Cocktail A. Removing sIL-4Rα from Cocktail A and adding IL-4 and IL-13 made Cocktail B, whereas adding IL-4 to Cocktail A gave Cocktail C. Adding IL-13 to Cocktail C gave Cocktail D." (PMID 37040185, 2023). "Furthermore, the concentration of endothelial cell adhesion molecules (such as vascular cell adhesion molecule-1 (VCAM-1) and intercellular adhesion molecule-1 (ICAM-1) is elevated in patients with COVID-19 and contributes to coagulation dysfunction." (PMID 37896963, 2023). "Using a more relaxed P-value threshold of 0.05, we found that expression level of one additional protein, ICAM1, showed marginal effect on COVID-19 severity in European ancestry (OR=1.136, 95%CI=1.059 to 1.218, P = 3.57 × 10−4) and in African ancestry (OR=1.481, 95%CI=1.008 to 2.176, P = 0.045)." (PMID 35772218, 2022). "Elevated concentrations of C5a, Galectin-3, ICAM-1 and VCAM-1 on presentation were associated with the composite outcome of ICU- admission or 30-day mortality in COVID-19 and controls, yet more pronounced in COVID-19." (PMID 36203596, 2022). "Also, the number of ICAM-1 + circulating EPCs appeared significantly increased in convalescent COVID-19 patients compared to healthy controls." (PMID 35397534, 2022). "Our study also highlights the value of ICAM1 in relation to COVID-19 severity in both ancestries." (PMID 35772218, 2022). "Moreover, in severe COVID-19 patients the plasma levels of adhesion molecules such as intercellular adhesion molecule 1 (I-CAM-1), vascular cell adhesion molecule-1 (VCAM-1), vascular adhesion protein-1 (VAP-1), were reported to be elevated." (PMID 35601094, 2022). "Finally, we will briefly discuss the role of ICAM-1 in other diseases, e.g., malaria and COVID-19, and the potential of anti-ICAM-1 therapies as illustrated in mitigating microbial infections in pre-clinical models." (PMID 35316427, 2022). "In severe COVID-19 patients, the plasma levels intercellular adhesion molecule 1 (I-CAM-1), vascular cell adhesion molecule-1 (VCAM-1), and vascular adhesion protein-1 (VAP-1), are elevated, indicating that the endothelial barrier is damaged consecutive to viral infection." (PMID 36519165, 2022). "One protein ICAM1 showed suggestive effect in both ancestries, where alternative splicing may be a mediator linking ICAM1 with COVID-19 severity." (PMID 35772218, 2022).